IL6 (interleukin 6)
Diseases named in the same sentence as IL6 in open-access papers (continued):
Sharing a sentence is not in itself a finding about the gene and the disease.
periodontitis (continued). "The levels of IL-2, IL-6 and IFN-γ were increased in saliva from RA patients compared to control subjects, both without periodontitis (P < 0.05)." (PMID 31182740, 2019). "We aimed to determine the levels of visfatin, interleukin-6 (IL-6) and tumor necrosis factor-alpha (TNF-α) in gingival crevicular fluid (GCF) in both obese/non-obese patients, with/without generalized chronic periodontitis (GCP)." (PMID 31365708, 2019). "We observed that the UWS concentration of IL-6 and TNF-α was not significantly different between T2DM and healthy individuals with no periodontitis." (PMID 29487749, 2018). "The results of the present study showed that FUCO administration did not have a significant effect on serum TNF-α, IL-1β, or IL-6 levels or local OPG activity, which increased significantly in rats with periodontitis." (PMID 27043583, 2016). "Some authors have shown higher serum IL-6 and TNF-α levels in healthy smokers when compared to the healthy nonsmokers and higher TNF-α levels in patients with periodontitis in comparison to the healthy controls." (PMID 25858079, 2015). "In line with these notions, increased periodontal expression of interleukin (IL)-6 and MMP-8 across patients with neither periodontitis nor T2DM, patients with periodontitis alone and patients with both diseases was reported by our group." (PMID 26581717, 2015). "The results support the hypothesis that proinflammatory cytokines, including IL-1α, IL-1β and IL-6, are likely to be involved in the pathogenesis of periodontitis and are good markers to evaluate the success of nonsurgical therapy in disease sites of patients with periodontitis." (PMID 24944641, 2014). "Similarly, SSc patients show elevated IL-6 levels in the GCF, but these do not correlate with any clinical parameters of periodontitis." (PMID 38779873, 2024). "However, in the current study, glyceryl 1,3 distearate failed to inhibit the overexpression of IL6 and IL8 in the periodontitis model." (PMID 39193343, 2024). "In particular, we hypothesized that the GCF levels of RANKL, OPG, IL-6, IL-17A, and MMP-8 do not change during this orthodontic treatment and are lower than those detected during periodontitis." (PMID 36902236, 2023). "In the present study, the levels of different pro-inflammatory and pro-destructive mediators common between periodontitis and orthodontics were quantified, and it was shown that the levels of the RANKL, OPG, IL-6, IL-17A, and MMP-8 do not vary during the 2 years of orthodontic treatment." (PMID 36902236, 2023). "An overexpression of miRNA-146 in patients with rapidly progressive aggressive periodontitis was shown to be accompanied by a reduction in the levels of TNF-α, IL-1β, and IL-6, which suggests the existence of a negative feedback loop between mi-146 and pro-inflammatory cytokine synthesis." (PMID 35269617, 2022). "It is important to note the discrepancies between the reports: in the case of IFNG, IL6, IL8, TNF, and TLR2, the differences in promoter methylation between patients with periodontitis and healthy individuals observed in some studies have not been reproduced in independent analyses." (PMID 33256844, 2020). "Therefore, the main objective of this study was to analyze the levels of visfatin, IL-6, and TNF-α in obese and non-obese individuals, with or without generalized chronic periodontitis (GCP)." (PMID 31365708, 2019). "Interestingly, in individuals with stable coronary artery disease and with chronic periodontitis, nonsurgical periodontal therapy decreased serum levels of TNF‐α, IL‐6 and CRP, which could help to reduce the inflammatory burden in these individuals." (PMID 39494478, 2024). "In wild‐type periodontitis mice, NAC‐S2 administration decreased the cemento‐enamel‐junction–alveolar bone crest (CEJ‐ABC) distance and the relative mRNA expression of TNF, IL‐6, and IL‐1β, while such phenomena could not be observed in TLR4 deficiency or Myd88 deficiency mice." (PMID 37647428, 2023).
periodontitis (continued). "IL‐6, a pro‐inflammatory cytokine that increases the migration of inflammatory cells and promotes osteoclast activity, has been shown to have equal levels in GCF in RA patients with periodontitis and periodontitis patients without RA and periodontally healthy patients." (PMID 33954982, 2021). "In our study, inhibition of PTEN expression with siRNA results in upregulation of IL1 and TNF-α, whereas the expression of IL6 was not significantly altered, suggesting that PTEN may exert anti-inflammatory effects in mouse periodontitis by modulating the expression of IL1 and TNF-α." (PMID 31886238, 2019). "Similar to these studies, our data demonstrated the down-regulation of pro-inflammatory cytokines (TNFα, IL-17, and IL-6) using cytokine cocktail-treated compared with non-cytokine-treated ADMPC, which have been reported to be involved in various inflammatory diseases, including periodontitis." (PMID 30696909, 2019).
Stroke (929 papers, 2006 to 2026). Sudden impairment of blood flow to a part of the brain due to occlusion or rupture of an artery to the brain. "Interleukin-6 (IL-6) is a key inflammatory mediator in ischemic stroke, and higher circulating IL-6 levels are associated with greater stroke severity and worse clinical outcomes." (PMID 42146493, 2026). "Circulating IL‐6 levels are significantly associated with ischemic stroke risk, with each SD increase in IL‐6 linked to a 19% higher incidence of stroke." (PMID 41567175, 2026). "IL‐6 associated with approximately 19% higher stroke risk per SD increase; hs‐CRP independently predicts events." (PMID 41567175, 2026). "Concurrently, large-scale epidemiological studies have confirmed that a sustained elevation of inflammatory markers such as C-reactive protein and IL-6 in post-stroke plasma is an independent risk factor for future cardiovascular events." (PMID 41601622, 2026). "It has also been observed that with increasing IL-6 levels in plasma, the risk of post-stroke delirium rises, which is characterized by acute, fluctuating changes in attention, awareness, and cognition." (PMID 40305179, 2025). "Elevated plasma IL-6 levels within the first 24 to 72 h of ischemic stroke are significantly associated with larger infarct volumes, greater stroke severity, and unfavorable outcomes at 90 days." (PMID 40949500, 2025). "Increased IL-6 levels are a recognized biomarker of various CNS disorders, including conditions associated with neuronal injury, such as stroke or traumatic brain injury, and are also commonly observed in patients with TLE." (PMID 41516142, 2025). "Genetic studies also underscore the relationship between IL-6 and atherosclerosis, a key risk factor for stroke." (PMID 40744929, 2025). "PPARα KO brains had upregulated expression of several genes already implicated in neural injury following stroke such as Mmp19, Il6, Saa3, and Il1r2." (PMID 40362325, 2025). "The risk of cognitive deterioration after stroke increased by as much as 95% for the highest IL-6 levels compared to the lowest." (PMID 40305179, 2025). "A large meta-analysis found that higher IL-6 levels were associated with an increased risk of future ischemic stroke, with stroke risk rising progressively in relation to IL-6 concentration." (PMID 40949500, 2025). "The findings also highlight the potential role of inflammatory biomarkers, particularly interleukin-6, as indicators of stroke risk in this population." (PMID 41362543, 2025). "CRP, an acute-phase reactant produced under IL-6 stimulation, is another well-established biomarker associated with stroke, with levels above 3.0 mg/L tripling stroke risk." (PMID 41362543, 2025). "Elevated levels of IL-6 in both the CSF and blood are linked to early neurological deterioration and worse outcomes following a stroke." (PMID 40142325, 2025). "IL-1β and TNF-α breach the BBB and cause neuronal cell death in stroke, while IL-6 and IL-8 enhance oxidative stress and secondary damage in TBI." (PMID 39861166, 2025). "IL-6, one of the most widely studied inflammatory markers, has been identified as a strong predictor of stroke risk; baseline IL-6 levels above 5 pg/mL increase the risk of vascular events 21-fold in patients with prior stroke who are not anticoagulated." (PMID 41362543, 2025). "It has been shown that an increase in IL-6 levels in the serum within the first 24 h after a stroke is associated with worsened functional status and poorer neurological outcomes in patients, as well as with the volume of damage." (PMID 40305179, 2025). "IL-6 is a key proinflammatory cytokine implicated in several neurological disorders, including stroke and epilepsy." (PMID 40807306, 2025). "Elevated levels of inflammatory cytokines (IL-18, CRP, IL-12, IL-6) in stroke patients are associated with a poor outcome." (PMID 40142325, 2025). "The primary objective was to assess the association between IL-6 and the incidence of stroke in the postoperative period." (PMID 41440557, 2025).
Stroke (continued). "Further bioinformatic analysis of our RNA-seq data revealed the upregulation of other genes in the IL6/JAK/STAT3 expression signatures in mouse stroke brains upon the loss of PPARα, as well." (PMID 40362325, 2025). "This is supported by other literature reports, indicating that IL-6 is a promising tool in reducing the risk of stroke." (PMID 40305179, 2025). "Long-term follow-up data revealed stroke and mortality incidences approaching 17.8%, directly related to high IL-6 levels, suggesting that biological risk persists beyond successful revascularization." (PMID 41440557, 2025). "Multivessel disease (PolyVD) combined with elevated IL-6 levels (≥2.64 pg/mL) facilitates the risk of stroke recurrence in patients with AIS or TIA after one year of observation." (PMID 40305179, 2025). "In population studies in humans, it has been shown that higher levels of IL-6 are associated with stroke risk factors and with a higher risk of AIS occurrence." (PMID 40305179, 2025). "Clinical meta‐analyses and cohort datasets have demonstrated that elevated levels of Il6, Il1β, Cxcl2, and Cxcl10 are closely associated with poorer stroke prognosis." (PMID 40585759, 2025). "This systematic review explored the association between prediabetes and stroke through significant biomarkers like IL-6, D-dimer, NSE and GFAP." (PMID 41150802, 2025). "An increase in IL-6 concentration was associated with an increased risk of stroke recurrence and disability within 90 days, with stroke recurrence mediating less than 20% of the association between IL-6 and functional outcome." (PMID 40305179, 2025). "Three latent profiles of psychoneurological symptom clusters exist in patients with a first stroke and are associated with markers of inflammation (interleukin-6 and hypersensitive C-reactive protein), thereby affecting their quality of life." (PMID 40709232, 2025). "Inflammatory biomarkers, particularly C-reactive protein (CRP) and IL-6, have been independently associated with poor stroke outcomes and reduced HRV." (PMID 40722730, 2025). "Within stroke pathology, inflammatory marker IL6 is associated with a greater incidence of post-stroke cerebral edema and an 18% increased risk of dying during hospitalisation compared to the overall mortality of 3.1%." (PMID 39337456, 2024). "Overall, increased IL-6 is observed in the setting of post-stroke neuroinflammation, which is associated with worse neurologic outcomes and cognitive impairment." (PMID 39063013, 2024). "Studies have identified inflammatory markers like CRP, IL-6, and IL-33 as predictors of initial stroke risk and post-stroke prognosis." (PMID 38169754, 2024). "Higher TNF-α and IL-6 levels in HbSS compared to HbAA are linked to increased vaso-occlusive crises and stroke risk." (PMID 39749215, 2024). "Patients with hypertension often exhibit elevated levels of inflammatory markers, including C-reactive protein and IL-6, which have been linked to a higher risk of stroke." (PMID 39144717, 2024). "A recent study in patients with ischemic stroke reported that BMI was inversely associated with IL-6 levels after major stroke, while eotaxin, IFN-β, IFN-γ, and TNF-α were upregulated when BMI increased." (PMID 38206990, 2024). "In patients with atrial fibrillation, IL-6 levels were higher in patients with increased plasma viscosity, and these patients have an increased risk of stroke." (PMID 38256155, 2024). "IL-6 is associated with recurrent stroke risk and poorer functional outcomes (as reflected by the mRS score within 1 year)." (PMID 39372701, 2024). "Inflammatory markers like C-reactive protein (CRP) and interleukin-6 (IL-6) have been associated with stroke severity and outcome." (PMID 39493062, 2024). "In the acute phase (day 2 after stroke), the rapid activation of pSTAT3 (increased IL-6 levels) in innate immune cell subsets was associated with poorer cognitive performance." (PMID 37728582, 2024).
Stroke (continued). "Within 6 to 12 h after cerebral ischaemia, the levels of TNF-α, IL-1β and IL-6 are increased in stroke patients and are associated with more severe neurological symptoms and poorer outcomes." (PMID 39198723, 2024). "Interleukin 6 (IL-6) is a marker of systemic inflammation that has been associated with functional outcome after stroke." (PMID 38732018, 2024). "In Italian patients, an increased risk of stroke was found in carriers of both the IL6–174GG and ICAM1 469E/E genotypes of the IL6–174 G > C (rs1800795) and ICAM1 469 E > K (rs5498) polymorphisms." (PMID 38638292, 2024). "Sensitivity analyses on different scales of IL‐6 concentrations showed similar results with previous analyses that IL‐6 was positively associated with the risk of stroke recurrence and functional disability." (PMID 37287421, 2023). "Higher relative concentrations of plasma CLEC4G, CKAP4, and IL-6 were associated with higher stroke severity, whereas LY75 and ITGA11 showed an inverse association." (PMID 37468969, 2023). "Association of IL‐6 with 90‐day disability mediated by follow‐up stroke recurrence on different sclaes of IL‐6." (PMID 37287421, 2023). "Subpopulations characterized by the inflammation indicators hs-CRP and IL-6 showed high risk of stroke recurrence, poor functional outcome, and mortality." (PMID 37248226, 2023). "The promoting effect of IL-17A on angiogenesis was associated with the expression of IL-6 during the stroke recovery stage." (PMID 36873773, 2023). "There were no significant sex differences in mean age, the distribution of APOE ε4 allele, stroke, hypertension, daily ActiGraph wear time, and serum concentrations of IL-6, IL-8, and TNF-α." (PMID 37491244, 2023). "Stroke recurrence mediates less than 20% of the association between IL‐6 and functional outcome at 90 days among patients with acute ischemic stroke." (PMID 37287421, 2023). "In this multi‐center cohort study, we found that the association between post‐stroke proinflammatory cytokine IL‐6 and functional disability at 90 days in patients with ischemic stroke was only partially mediated by follow‐up stroke recurrence." (PMID 37287421, 2023). "IL-1β has been associated with exacerbation of injury in stroke and has been implicated in the pathogenic processes associated with a number of central nervous system disorders, while IL-6 and IL-10 have been found to be neuroprotective." (PMID 36969226, 2023). "This study demonstrated the relationship between levels of IL-6 and high-risk plaque features associated with stroke risk." (PMID 37762627, 2023). "In the context of secondary prevention, the risk of stroke recurrence due to elevated Lp(a) was significantly reduced when LDL-C or interleukin-6 levels were kept low." (PMID 37251802, 2023). "The mediated proportion of the association between IL‐6 and functional disability by stroke recurrence was 18.72% (95% CI, 9.26%–28.18%) in the adjusted model." (PMID 37287421, 2023). "Because of the low likelihood of confounding inherent in the genetic epidemiological design, these findings suggest IL-6 has a directly causal role in stroke pathogenesis." (PMID 41541100, 2023). "Studies have shown that IL-6 is not only an independent risk factor for post-stroke neuropathological damage, but is closely related to stroke recurrence." (PMID 37098609, 2023). "First, IL6, a proinflammatory cytokine, was found to be positively associated with both stroke severity as measured by NIHSS and mRS, the latter being a novel finding." (PMID 37468969, 2023). "In BISC, higher IL-6 levels were associated with recurrent MACE and stroke in those whose index event was of undetermined cause (IL-6, MACE: RR 1.78, 95% CI 1.19-2.66; IL-6, recurrent stroke: RR 1.65, 95% CI 1.09–2.5; CRP, MACE: RR 1.45, 95%CI 1.04–2.03)." (PMID 41541100, 2023). "The indirect effect of IL‐6 via follow‐up stroke recurrence implied a 4% increased risk of functional disability (aOR 1.04; 95% CI, 1.02–1.06) would be observed on average." (PMID 37287421, 2023).